THBD (thrombomodulin)
Diseases named in the same sentence as THBD in open-access papers (continued):
Sharing a sentence is not in itself a finding about the gene and the disease.
malaria (14 papers, 2009 to 2024). Malaria is a serious and sometimes fatal disease caused by a parasite that commonly infects a certain type of mosquito which feeds on humans. "In lung specimens obtained from patients who died from severe malaria-associates ARDS, the anticoagulant properties, as characterised by EPCR and thrombomodulin, were dysregulated." (PMID 38791043, 2024). "Malaria-infected erythrocytes cause the loss of EPCR and thrombomodulin in brain vessels, leading to subsequent fibrin deposition within the microvasculature, which impacts the severity of cerebral malaria." (PMID 35100311, 2022). "Endothelial damage and dysfunction have been evidenced by increased levels of soluble adhesion molecules (e.g., sICAM-1, sVCAM-1 and sE-Selectin) and thrombomodulin (sTM), and reduced levels of nitric oxide (NO) in the plasma of patients with malaria." (PMID 23349902, 2013). "The susceptibility difference and parity-specific associations of ABO phenotypes with placental malaria might be due to the effect of the ABO phenotype on the level of the proteoglycan thrombomodulin, which is present in the placenta and mediates the binding of malaria-infected RBCs with CSA." (PMID 38037059, 2023). "BOEC’s derived from cryopreserved small-volume PBMC samples from Ghanaian malaria patients (n = 8) all expressed EPCR, ICAM-1, thrombomodulin and PECAM-1." (PMID 30300360, 2018).
acute respiratory distress syndrome (11 papers, 2015 to 2024). Progressive and life-threatening pulmonary distress in the absence of an underlying pulmonary condition, usually following major trauma or surgery. "Altered plasma levels of protein C, thrombomodulin, and the endothelial protein C receptor are associated with poor clinical outcomes in patients with acute respiratory distress syndrome (ARDS)." (PMID 27215212, 2016). "The administration of recombinant human soluble thrombomodulin (rhTM), which has both anti-inflammatory and anticoagulant activities, improves outcomes and respiratory function in patients with acute respiratory distress syndrome." (PMID 27826444, 2016). "Recombinant human soluble thrombomodulin (rhTM) demonstrates anticoagulation effects superior to heparin for the treatment of disseminated intravascular coagulation (DIC) and improves the outcomes and respiratory functions in patients with sepsis-induced acute respiratory distress syndrome (ARDS)." (PMID 27826444, 2016).
Cirrhosis (11 papers, 2011 to 2025). A chronic disorder of the liver in which liver tissue becomes scarred and is partially replaced by regenerative nodules and fibrotic tissue resulting in loss of liver function. "In patients with stable decompensated cirrhosis, the synergy between platelet PN-1 and thrombomodulin to inhibit thrombin generation, observed in healthy individuals, was lost." (PMID 41281442, 2025). "In the presence of thrombomodulin, thrombin generation of the patients with cirrhosis was more resistant than in the controls group in both whole blood and plasma, although the inhibitory effect of thrombomodulin was weaker in whole blood than in plasma." (PMID 34066706, 2021). "Studies have shown that the balance of procoagulants and anticoagulants in patients with cirrhosis was normal when thrombin generation was measured in presence of thrombomodulin even though PT and APTT were prolonged." (PMID 24396346, 2013). "Previous studies have proposed that the hypercoagulability of blood may be more severe in patients with cirrhosis with poorer liver function because of their resistance to thrombomodulin activity, a critical factor mediating the anticoagulation process." (PMID 36387035, 2022). "Hypercoagulability in cirrhosis is likely due to an elevated factor VIII to protein C ratio and thrombomodulin resistance." (PMID 39518754, 2024). "PT and aPTT assays, which detect only 5% thrombin formation without thrombomodulin, do not reflect activated protein C levels, which are crucial for anticoagulation in cirrhosis." (PMID 39518754, 2024).
Hypertension (11 papers, 2014 to 2023). The presence of chronic increased pressure in the systemic arterial system. "In this study, patients with carotid atherosclerosis had a higher mean age and a higher prevalence of hypertension, which could contribute to the association between high levels of soluble thrombomodulin and carotid atherosclerosis." (PMID 32642566, 2020). "The study by Sharma and colleagues found that two intergenic single nucleotide polymorphisms (SNPs) that regulate both thrombomodulin and CD93 levels, and CD93 SNPs rs7492 and rs2749812, were associated with hypertension at high altitude." (PMID 37371490, 2023). "Age, blood pressure, blood urea nitrogen, creatinine, C-reactive protein, soluble thrombomodulin, pentraxin 3, frequency of hypertension, hematuria, and proteinuria were significantly higher in patients with AAV than in the controls." (PMID 35160215, 2022). "The SNPs with the highest risk towards hypertension were intergenic SNPs rs1006472 of CD8B2;ST6GAL2, and rs1998081 and rs2424515 of THBD;CD93." (PMID 34575042, 2021). "Additional module associations in AFR were detected with traits and outcomes including MI, hypertension, thrombomodulin, and thrombin-antithrombin complex." (PMID 34252155, 2021). "The acquired results—significantly higher systolic and mean blood pressure values in patients with higher thrombomodulin levels—prove the well-known influence of hypertension on endothelial damage." (PMID 29682152, 2018). "In the univariable logistic regression, the following factors were associated with carotid atherosclerosis: age > 45 years (OR = 12.0, 95% CI: 1.4–98.8, p = .02), hypertension (OR = 3.8, 95% CI: 1.2–12.1, p = .02), and high-level of soluble thrombomodulin (OR = 3.4, 95% CI: 1.2–10.0, p = .02)." (PMID 32642566, 2020). "However, interventions with ACE-targeting antibodies have led to hypertension, cough, and edema while targeting thrombomodulin can trigger thrombosis." (PMID 30854484, 2019). "This suggests that regulation of renal thrombomodulin expression is independent of hypertension-mediated endothelial damage, which was also supported by the lack of increased thrombomodulin expression in our hypertensive control patients." (PMID 33707524, 2021).
Stroke (11 papers, 2004 to 2024). Sudden impairment of blood flow to a part of the brain due to occlusion or rupture of an artery to the brain. "Mediated by its pro-inflammatory activity, TS exposure has been previously shown to promote thrombomodulin downregulation and to increase the risk of blood clot formation and stroke." (PMID 32340626, 2020). "The genes encoding proteins in the thrombomodulin-protein C pathway are promising candidate genes for stroke susceptibility because of their importance in thrombosis regulation and inflammatory response." (PMID 15574195, 2004). "Using data from the Stroke Prevention in Young Women Study, we sought to determine the association between the THBD Ala455Val polymorphism and the occurrence of ischemic stroke in young women." (PMID 15574195, 2004). "Using data from the Stroke Prevention in Young Women Study, we sought to determine the association between the Ala455Val thrombomodulin polymorphism and the occurrence of ischemic stroke in young women." (PMID 15574195, 2004). "Our results are also consistent with a causal association between stroke and the THBD Ala455Val polymorphism, thereby defining a susceptibility locus for the disease." (PMID 15574195, 2004). "A few studies have shown that the THBD Ala455Val polymorphism is associated with ischemic heart disease, but we know of no prior reports examining this polymorphism's association with stroke." (PMID 15574195, 2004). "Because of the central role that the thrombomodulin-protein C pathway plays in thrombosis regulation and inflammatory response, the genes encoding these pathway proteins are promising candidate genes regarding stroke susceptibility." (PMID 15574195, 2004). "TFPI 536C>T as well as THBD 127G>A was found in one stroke patient (0.7%) and one MI/PAOD patient (1.6%)." (PMID 28649568, 2017). "Furthermore, modules of loci were associated with clinical traits and blood biomarkers including previous number of strokes, prothrombin fragments 1 + 2, thrombomodulin, thrombin-antithrombin complex, triglyceride levels, and tissue plasminogen activator." (PMID 34252155, 2021). "As smoking can increase the level of VWF and decrease the level of thrombomodulin, there could be a correlation between smoking and stroke occurrence in COVID-19 patients." (PMID 32486196, 2020). "Using a cross-sectional design, we measured plasma levels of intercellular adhesion molecule-1 (ICAM-1), plasminogen activator inhibitor-1 (PAI-1), vascular endothelial growth factor (VEGF), and soluble thrombomodulin (sTM) in stroke patients and controls, stratified by HIV status." (PMID 30697583, 2019). "Several published studies have shown that the Ala455Val thrombomodulin polymorphism is associated with ischemic heart disease, but none has examined the association with stroke." (PMID 15574195, 2004). "Thrombomodulin has not previously been examined as a candidate gene for stroke susceptibility." (PMID 15574195, 2004).
acute kidney injury (10 papers, 2014 to 2026). Sudden and sustained deterioration of the kidney function characterized by decreased glomerular filtration rate, increased serum creatinine or oliguria. "Area under the receiver operating characteristic curves (AUROC) for day-1 plasma levels of angiopoietin-2 and thrombomodulin in predicting development of acute kidney injury." (PMID 36354140, 2022). "In addition, although blood thrombomodulin levels reportedly reflect vascular endothelial damage, thrombomodulin is a renal metabolite and should be assessed with caution, because renal failure will increase blood levels of thrombomodulin regardless of vascular endothelial damage." (PMID 35328761, 2022).
ischemic stroke (10 papers, 2004 to 2024). A stroke disorder caused by obstruction of blood flow to the brain, due to thrombotic (local blood clot formation) or embolic (due to a blood clot or other material traveling from another site) event. "Thrombomodulin has been shown to be associated with cerebrovascular ischemic events and can be considered an important biomarker for the acute onset of ischemic stroke." (PMID 38248346, 2024). "High levels of plasma homocysteine are also associated with DNA hypermethylation of thrombomodulin in patients with ischemic stroke." (PMID 35741740, 2022). "The serum concentration of soluble thrombomodulin decreased at the acute stage and increased after six months of ischemic stroke onset, as shown in a clinical study." (PMID 36085043, 2022). "Here we pursue an a priori hypothesis that genetic variation in the endothelial-based receptors of the thrombomodulin−protein C system (THBD and PROCR) may similarly be associated with early-onset ischemic stroke." (PMID 30383853, 2018). "PROCR, but not THBD, polymorphisms are associated with early-onset ischemic stroke in young Caucasians." (PMID 30383853, 2018). "Thrombomodulin analogues for the treatment of ischemic stroke." (PMID 21645225, 2011). "To this end we tested the hypothesis that THBD (OMIM 188040) and PROCR (OMIM 600646) variants are associated with early-onset ischemic stroke using a 2-stage discovery and replication design, and then addressed whether the identified variants also associated with older-onset disease." (PMID 30383853, 2018).
breast cancer (9 papers, 2013 to 2024). A primary or metastatic malignant neoplasm involving the breast. "We have shown that circulating biomarkers of inflammation, hypercoagulability, and endothelial injury, including C-reactive protein (CRP), thrombomodulin (TM), and thrombin–antithrombin complex (TAT), correlated with the risk of DOX-induced cardiotoxicity in breast cancer patients." (PMID 39273682, 2024). "This suggests that thrombomodulin Fc fusion protein administered exogenously at a relatively early stage of inflammation may be applied to the development of new therapies that inhibit the binding of β1 integrin of breast cancer cell lines to fibronectin." (PMID 33562346, 2021). "In breast cancer, cDC1-related genes were substantially upregulated in the high SLAMF6 group than in the low SLAMF6 group except for THBD." (PMID 38287061, 2024). "Recently, thrombomodulin was reported to be able to bind extracellular matrix proteins, such as fibronectin and collagen; however, whether thrombomodulin regulates the binding of human breast cancer-derived cell lines to the extracellular matrix remains unknown." (PMID 33562346, 2021). "A statistically significant increase was noted for NET nucleosomes, thrombin–antithrombin complex (TAT), thrombomodulin (TM), and CRP in breast cancer patients with reduced LVEF > 10% (p < 0.05) compared to the patients with normal LVEF in response to DOX-based chemotherapy." (PMID 37444400, 2023). "Consequently, CD8+ T-cell effector (Teff) score, comprising gene expression of IFNG, PRF1, CD8A and CD8B, and BATF3-DC score, calculated with the expression level of BATF3, IRF8, THBD, CLEC9A, and XCR118 were markedly increased in the high SLAMF6 group than in the low SL AMF6 group in breast cancer." (PMID 38287061, 2024).
myocardial infarction (9 papers, 2014 to 2025). Gross necrosis of the myocardium, as a result of interruption of the blood supply to the area, as in coronary thrombosis. "Thrombomodulin polymorphism −33G>A was reported as a determinant of myocardial infarction susceptibility in Asia." (PMID 28811939, 2017). "A study in Korea revealed that carriers of −33G>A thrombomodulin polymorphism had 4.63 times higher susceptibility to myocardial infarction." (PMID 28811939, 2017). "Furthermore, analysis between thrombomodulin −33G>A polymorphism and myocardial infarction suggested that carriers of GG genotype had similar risk factor of myocardial infarction compared to that of AG/AA genotype." (PMID 28811939, 2017). "Hence, this study was designed to investigate the correlation of ABO polymorphism and thrombomodulin polymorphism −33G>A with the incidence of acute myocardial infarction (AMI)." (PMID 28811939, 2017). "Hence, this study was designed to investigate the correlation of ABO polymorphism and thrombomodulin polymorphism −33G>A with the incidence of acute myocardial infarction in Javanese men." (PMID 28811939, 2017). "Thus, we evaluated associations between six novel markers (E-Selectin, P-Selectin, thrombomodulin, thrombopoietin, intercellular adhesion molecule 3 and GPIIb/IIIa) and established cardiovascular risk factors as well as the risk of myocardial infarction (MI) in a population-based study." (PMID 30816120, 2019). "Vitamin D can contribute to thrombomodulin and tissue factor expression regulation, leading to an anticoagulant effect and preventing thrombogenic activity, one of the factors most responsible for myocardial infarction." (PMID 37571241, 2023). "A study of patients with acute myocardial infarction (AMI) found that plasma angiopoietin 2 (Ang-2) levels (6338.28 ± 5862.77 versus 2412.03 ± 1256.58 pg/mL) and thrombomodulin (TM) levels (7.6 ± 2.26 versus 5.34 ± 2.0 ng/mL) were higher in patients with AKI than in those without AKI." (PMID 36431113, 2022).
viral infections (9 papers, 2014 to 2022). "A similar upregulation upon virus infection and subsequent downregulation by US2 was observed for thrombomodulin in HFF cells." (PMID 25875600, 2015).
colorectal cancer (8 papers, 2006 to 2024). A primary or metastatic malignant neoplasm that affects the colon or rectum. "Furthermore, abnormal methylation of THBD may be associated with gastric and colorectal cancer development." (PMID 38809929, 2024). "Moreover, a recent genome-wide screen using DNA methylation data from more than 700 colorectal cancer samples identified hypermethylation of the thrombin receptor THBD and of C9orf50 as novel blood-based biomarkers for colorectal cancer detection." (PMID 25473433, 2014). "cfDNA samples were obtained from xenografted mice that were inoculated with one of two human colorectal cancer cell lines, SW620 and SNU407, which were analyzed for the methylation status of THBD and SLIT3 using a MethyLight assay." (PMID 33396258, 2020). "Soluble thrombomodulin (TMα), known to degrade HMGB1 in a thrombin-dependent manner, prevents CIPN in rodents treated with paclitaxel, oxaliplatin, or vincristine and in patients with colorectal cancer undergoing oxaliplatin-based chemotherapy." (PMID 33396481, 2020). "A genome-wide scale study with plasma and serum samples from 107 colorectal cancer patients and 98 individuals without colorectal cancer revealed that analysis of methylated THBD and C9orf50 outperformed carcinoembryonic antigen (CEA) measurement for early colorectal cancer detection." (PMID 23681012, 2013).
bladder cancer (7 papers, 2006 to 2025). "This study aimed to evaluate the association between thrombomodulin (TM)–positive cell rate (PR) and tumor grade, stage, and recurrence in patients with bladder cancer." (PMID 40746927, 2025). "The overarching objective was to assess the potential of thrombomodulin as a prognostic biomarker to aid in predicting outcomes and improving patient management in bladder cancer." (PMID 40746927, 2025).
coronary artery disease (7 papers, 2004 to 2024). "We also measured the soluble thrombomodulin, which had been detected as a potential marker of endothelial injury and risk factor of coronary heart disease." (PMID 39125657, 2024). "A previous study suggested that in coronary artery disease individuals, the use of cholesterol-lowering drugs can significantly upregulate thrombomodulin gene expression, whereas TNF-α and NF-κB were significantly downregulated." (PMID 36012347, 2022). "Genotypes comparison of C1418T of Thrombomodulin Gene in Patients with Coronary artery disease and in Control Subjects." (PMID 30034448, 2018). "During the last several decades, some studies suggested that non-O blood group and thrombomodulin polymorphism −33G>A are the risk factors of coronary artery disease especially in Asia." (PMID 28811939, 2017).
thromboembolic disease (7 papers, 2013 to 2024). "A mutation in the thrombomodulin (THBD) gene is the main cause of thromboembolic disease." (PMID 33195475, 2020). "It has been noted that thromboembolic complications are challenging to control in EM, particularly due to the release of eosinophilic granular proteins, which could neutralize thrombomodulin's local anticoagulant activity, resulting in intracavitary thrombosis and thromboembolism." (PMID 38966441, 2024). "Previous reports showed that soluble thrombomodulin levels were increased in patients with CMV infection and thromboembolic disease." (PMID 38255886, 2024).
vasculitis (7 papers, 2010 to 2026). "Proposed as a marker for endothelial cell damage, thrombomodulin has been associated with active vasculitis in SLE and correlated significantly and positively with SLEDAI score." (PMID 31651352, 2019). "Importantly, thrombomodulin is being considered as a marker for EC damage and has been linked to active vasculitis in SLE." (PMID 39242108, 2024). "Biomarkers such as soluble thrombomodulin and pentraxin 3 are indicative of vascular endothelial damage, and their levels rise in systemic vascular disorders like DIC and vasculitis." (PMID 38255886, 2024).